UBE4A (ubiquitination factor E4A)
Description:
Ubiquitin-protein ligase that probably functions as an E3 ligase in conjunction with specific E1 and E2 ligases. May also function as an E4 ligase mediating the assembly of polyubiquitin chains on substrates ubiquitinated by another E3 ubiquitin ligase. Mediates 'Lys-48'-linked polyubiquitination of substrates.
Synonyms: KIAA0126; UBOX2; UFD2; E4; NEDHMS
Tractability: PROTAC: ubiquitination databases record sites on it; its protein half-life has been measured.
Target class: Enzyme; Transferase
Gene: Protein-coding gene on chromosome 11 (118,359,587 to 118,399,211, forward strand). Ensembl gene ENSG00000110344.
Subcellular location: Cytoplasm
Subcellular location (Human Protein Atlas): Nuclear speckles
Pathways (Reactome):
Immune System: Antigen processing: Ubiquitination & Proteasome degradation
Gene Ontology:
Molecular function: protein binding; ubiquitin protein ligase activity; ubiquitin-ubiquitin ligase activity; ubiquitin-protein transferase activity
Biological process: ERAD pathway; protein polyubiquitination; ubiquitin-dependent protein catabolic process; protein ubiquitination
Cellular component: cytoplasm; ubiquitin ligase complex
Genetic constraint (gnomAD): Loss-of-function variants: 45 observed, 116.45 expected, observed/expected ratio (o/e) 0.39, 90% interval 0.3 to 0.5. The upper end of that interval is the gene's LOEUF score, 0.5, which puts it in group 2 of 6, group 1 being the genes least tolerant of losing a copy. Missense variants: 1,064 observed, 1,343.5 expected, observed/expected ratio (o/e) 0.79, 90% interval 0.75 to 0.83. Synonymous variants: 407 observed, 471.62 expected, observed/expected ratio (o/e) 0.86, 90% interval 0.8 to 0.94.
Homologues: Orthologues: chimpanzee UBE4A (99% identical), macaque UBE4A (99% identical), dog UBE4A (99% identical), guinea pig UBE4A (99% identical), rabbit UBE4A (98% identical), pig UBE4A (98% identical), mouse Ube4a (97% identical), rat Ube4a (94% identical), tropical clawed frog ube4a (81% identical), zebrafish ube4a (77% identical), Drosophila melanogaster Ube4A (34% identical). Paralogues in human: UBE4B (25% identical).
Diseases named in the same sentence as UBE4A in open-access papers:
UBE4A is named in the same sentence as 15 diseases in open-access papers, as found by Europe PMC text mining. Sharing a sentence is not in itself a finding about the gene and the disease. The quoted sentences say what the papers report.
colorectal cancer (4 papers, 2017 to 2026). A primary or metastatic malignant neoplasm that affects the colon or rectum. "UBE4A has previously been shown to promote colorectal cancer cell proliferation, though its role in Treg cells remains unexplored." (PMID 41535263, 2026). "UBE4A-SLAP has been shown to ubiquitylate EphA2 in cells and in vitro, and knockdown of SLAP or of UBE4A slightly increased total EphA2 protein in colorectal cancer cell lines." (PMID 28883622, 2017).
prostate carcinoma (3 papers, 2019 to 2025). A carcinoma that arises from epithelial cells of the prostate gland. "The ubiquitin ligase UBE4A inhibits prostate cancer progression by targeting interleukin-like EMT inducers." (PMID 40299526, 2025). "In fact, the ubiquitin ligase UBE4A inhibits prostate cancer progression by regulating ILEI1 expression, a protein required for metastatic progression in prostate cancer cells." (PMID 30972102, 2019). "UBE4A represses ILEI protein expression to inhibit prostate cancer progression." (PMID 35136024, 2022).
thyroid cancer (2 papers, 2022). "However, in thyroid carcinoma, UBE4A was reported as a ubiquitin ligase that is inversely correlated with PCBP1 protein expression and promotes cancer progression." (PMID 35136024, 2022). "From their observations, the authors concluded that UBE4A-regulated ubiquitination and degradation of PCBP1 may be involved in the tumorigenesis of thyroid cancer." (PMID 35406382, 2022).
atherosclerosis (1 paper, 2024). A disease characterized by the build-up of fatty material and calcium deposition in the arterial wall resulting in partial or complete occlusion of the arterial lumen. "In contrast, deletion of IP6K1 in hepatocytes enhances apoA-I production by preventing UBE4A-mediated apoA-I degradation, and subsequent attenuates atherosclerosis." (PMID 39643078, 2024).
colitis (1 paper, 2026). Inflammation of the colon. "Mechanistically, TNFR2 signaling elevated TRIP13 expression, which stabilized HAT1 protein by preventing UBE4A-mediated polyubiquitination degradation of HAT1, thus promoting Treg proliferation and protecting against colitis." (PMID 41535263, 2026).
Crohn disease (1 paper, 2022). A gastrointestinal disorder characterized by chronic inflammation involving all layers of the intestinal wall, noncaseating granulomas affecting the intestinal wall and regional lymph nodes, and transmural fibrosis. "For instance, two enteroendocrine markers, ubiquitination factor E4A (UBE4A) and paired-like homeobox 2b (Phox2B), are reported to significantly augment the distal ileum of patients with Crohn’s disease." (PMID 35050153, 2022).
dementia (1 paper, 2017). Loss of intellectual abilities interfering with an individual's social and occupational functions. "Targeted re-sequencing of the six candidate genes (LTF, MME, UBE4A SORL1, FAM221A and KDM2B) was performed in 35 EOAD cases with a family history of dementia." (PMID 28595629, 2017).
Hepatic steatosis (1 paper, 2024). Steatosis is a term used to denote lipid accumulation within hepatocytes. "On the other hand, deleting UBE4A causes severe defects in animal models such as neuronal developmental defects, insulin resistance and hepatic steatosis, suggesting that UBE4A may not be a suitable treatment target for metabolic disease." (PMID 39643078, 2024).
cancer (3 papers, 2022 to 2024). A tumor composed of atypical neoplastic, often pleomorphic cells that invade other tissues.
UBE4A also shares sentences with these, for which no sentence is quoted: colon cancer (1 paper); diabetes (1); gallbladder cancer (1); gastric cancer (1); metabolic disease (1); tumor (1).